ABHD17A (abhydrolase domain containing 17A, depalmitoylase)
Description:
Hydrolyzes fatty acids from S-acylated cysteine residues in proteins. Has depalmitoylating activity towards NRAS. Has depalmitoylating activity towards DLG4/PSD95. May have depalmitoylating activity towards MAP6 (By similarity).
Synonyms: C19orf27; FAM108A1; MGC5244
Tractability: Antibody: UniProt places it where antibodies can reach, with high confidence; its Gene Ontology location is reachable by antibodies, with high confidence. PROTAC: ubiquitination databases record sites on it; its protein half-life has been measured.
Gene: Protein-coding gene on chromosome 19 (1,876,810 to 1,885,618, reverse strand). Ensembl gene ENSG00000129968.
Subcellular location: Cell membrane; Endosome membrane; Cell projection, dendritic spine; Postsynaptic density membrane
Subcellular location (Human Protein Atlas): Vesicles; Nuclear speckles
Pathways (Reactome):
Signal Transduction: RAS processing
Gene Ontology:
Molecular function: palmitoyl-(protein) hydrolase activity; protein binding
Biological process: negative regulation of NLRP3 inflammasome complex assembly; protein depalmitoylation; protein localization to membrane; negative regulation of protein localization to microtubule; negative regulation of skeletal muscle tissue regeneration; negative regulation of vesicle fusion; positive regulation of protein localization to endosome; regulation of postsynapse organization
Cellular component: endosome membrane; membrane; plasma membrane; postsynaptic density membrane; dendritic spine; glutamatergic synapse; postsynaptic density; postsynaptic recycling endosome membrane; recycling endosome membrane
Genetic constraint (gnomAD): Loss-of-function variants: 8 observed, 18.44 expected, observed/expected ratio (o/e) 0.43, 90% interval 0.25 to 0.78. The upper end of that interval is the gene's LOEUF score, 0.78, which puts it in group 3 of 6, group 1 being the genes least tolerant of losing a copy. Missense variants: 273 observed, 349.98 expected, observed/expected ratio (o/e) 0.78, 90% interval 0.71 to 0.86. Synonymous variants: 158 observed, 156.24 expected, observed/expected ratio (o/e) 1.01, 90% interval 0.89 to 1.15.
Homologues: Orthologues: macaque ABHD17A (99% identical), dog ABHD17A (94% identical), guinea pig ABHD17A (93% identical), pig ABHD17A (93% identical), mouse Abhd17a (92% identical), chimpanzee ABHD17A (88% identical), zebrafish abhd17ab (84% identical), zebrafish abhd17aa (81% identical), rat Klf16 (77% identical), tropical clawed frog abhd17a (76% identical), Drosophila melanogaster CG33096 (63% identical), Caenorhabditis elegans aho-3 (53% identical). Paralogues in human: ABHD17C (76% identical), ABHD17B (73% identical), ABHD12 (24% identical), ABHD12B (23% identical), ABHD13 (19% identical), ABHD16A (17% identical), ABHD16B (16% identical).
Diseases named in the same sentence as ABHD17A in open-access papers:
ABHD17A is named in the same sentence as 4 diseases in open-access papers, as found by Europe PMC text mining. Sharing a sentence is not in itself a finding about the gene and the disease. The quoted sentences say what the papers report.
viral disease (1 paper, 2025). "Our work therefore elucidated the unconventional role of depalmitoylase ABHD17A in elevating the S-palmitoylation modification, expanded the biological functions of ABHD17A in innate immunity, and provided potential targets for viral disease therapy." (PMID 40723864, 2025).
viral infection (1 paper, 2025). "In the present study, we elucidated an unprecedented function of depalmitoylase ABHD17A in virus infection." (PMID 40723864, 2025). "Altogether, our study fills the gap in our knowledge of the cellular function of ABHD17A in viral infection and provides new insight into the mechanism of ABHD members in the dynamic S-palmitoylation of IFITM protein." (PMID 40723864, 2025). "Together, our findings highlight the unconventional machinery by which ABHD17A facilitates the S-palmitoylation of IFITM1 to inhibit various viral infections, which also reveals a previously unknown virological function of ABHD17A in innate immunity." (PMID 40723864, 2025).
cancer (5 papers, 2020 to 2025). A tumor composed of atypical neoplastic, often pleomorphic cells that invade other tissues. "ABHD17A has been reported to exert depalmitoylase activity for 10 years, it participates in multiple biological processes such as cancer growth, synapse development, and inflammation by removing palmitoyl groups from substrates." (PMID 40723864, 2025). "More recently, regulation of the palmitoylation status of the transcription factor TEAD, which is depalmitoylased by ABHD17A, has been suggested to be a potential target for controlling TEAD-dependent processes, including cancer cell growth." (PMID 32245826, 2020). "Thus, as very little is known about ABHD17A and DPH6 in the context of cancer, it is difficult to precisely speculate how they may be playing a role in tumor cell extrinsic regulation of metastatic colonization." (PMID 32245826, 2020). "Furthermore, an analysis of the relationship between infiltration estimation and gene expression in gene modules revealed that T-cell CD4+ Th1 in genes ERRFI1, ZBED5, UQCRC2, ZNF146, ABHD17A, YWHAZ, and especially PLSCR4 showed a negative correlation in nearly 40 types of cancer." (PMID 38464509, 2024).
ABHD17A also shares sentences with these, for which no sentence is quoted: tumor (1 paper).